BRAF (B-Raf proto-oncogene, serine/threonine kinase)
Diseases named in the same sentence as BRAF in open-access papers (continued):
Sharing a sentence is not in itself a finding about the gene and the disease.
thyroid cancer (continued). "As a result, glutamine metabolism of BRAF-mutant thyroid cancer cells is reprogrammed due to down-regulation of c-Myc downstream glutamine transporter and glutaminases, thereby making these cells more sensitive to glutamine deprivation and glutaminase inhibitor." (PMID 37479689, 2023). "This approach is a potential strategy for the treatment of BRAF mutant thyroid cancer." (PMID 37325052, 2023). "This study will provide a potential therapeutic strategy for BRAF-mutant thyroid cancers." (PMID 37479689, 2023). "Targeting the β-catenin signaling pathway may have significant therapeutic benefits for BRAF-mutant thyroid cancer by not only inhibiting tumor growth but also enhancing host immune surveillance." (PMID 37483610, 2023). "In thyroid cancer, Angell and colleagues demonstrated that there was a tendency for BRAF mutant tumors to have higher CD163 expression than CD80, but they also reported that this varied significantly between patients, with some having higher CD80 and others CD163." (PMID 37686663, 2023). "Statistical analysis of the basal profiles yielded five peptides (ADDB_696-708, ERF_519-531, GSUB_61-73, LMNB1_16-28, and PP2AB_297-309) that showed a significantly different signal (p < 0.05, FDR 76%) and was able to differentiate BRAF V600E from non-BRAF V600E thyroid cancers." (PMID 37760447, 2023). "However, its biological role in thyroid cancer and its effect on the cellular response of BRAF-mutant thyroid cancer cells to BRAF/MEK inhibitors remains totally unclear." (PMID 37479689, 2023). "The concept of combining HSP90 inhibition with BRAF inhibition appeared more than a decade ago and despite seemingly favorable results in early preclinical studies, this combination strategy has yet to be developed further within the thyroid cancer field." (PMID 37803074, 2023). "Many genes are differentially methylated irrespective of BRAF V600E mutation status; however, there are also BRAF-mutation-specific genes that show a markedly different magnitude of methylation in thyroid cancer tissue." (PMID 36975440, 2023). "Many fundamental mutations in thyroid cancer target different constituents of the MAPK signaling pathway, including BRAF V600E and RAS gene point mutations, RET::PTC and PAX8::PPARγ chromosomal rearrangements, and telomerase reverse transcriptase (TERT) promoter mutations." (PMID 36672362, 2023). "Furthermore, vemurafenib and dabrafenib were specifically designed to target this mutant and are effective against BRAF V600E-positive thyroid cancer." (PMID 37760447, 2023). "BRAF, TERT and RAS gene mutations were frequently observed in thyroid cancer." (PMID 37745716, 2023). "Mechanistically, knocking down STAG2 in BRAF-mutant thyroid cancer cells decreases the protein stability of c-Myc via the ERK/AKT/GSK3β feedback pathway, thereby impairing glutamine metabolism of thyroid cancer cells by down-regulating its downstream targets such as SCL1A5, GLS and GLS2." (PMID 37479689, 2023). "If our finding is confirmed by gene expression data in a future study, then one may consider investigating the effect of TNFR2-targeted antibody therapy in BRAF mutant thyroid cancer patients in the case of RAI failure." (PMID 36975440, 2023). "Hence, we exploited the glycolytic dependency of BRAF-driven thyroid carcinomas using combinations of NSAIDs and BRAFi." (PMID 37198319, 2023). "In this work, we have demonstrated that patients with intermediate-risk thyroid carcinoma, treated with thyroid surgical resection and RIT, have a significantly higher risk of displaying an LER to radioiodine treatment when harboring a BRAF mutation (p = 0.001)." (PMID 37373171, 2023). "To experimentally verify the transcriptional effect of VMR on metabolic genes in the context of thyroid carcinomas, we evaluated if PLX4032—a VMR analogue—could repress the expression of glycolysis-related genes in a BRAF-mutated PTC cell line." (PMID 37198319, 2023).
thyroid cancer (continued). "Moreover, HER3 was by far the dominant RTK activated in a phospho-array RTK screen of BRAF-mutant thyroid cancer cell lines treated with vemurafenib." (PMID 36476495, 2022). "With the dramatic development of molecular diagnostic technologies in recent years, researchers have discovered BRAF, RAS, and telomerase reverse transcriptase (TERT) promoter mutations, RET/PTC rearrangement, and other genetic mutations to be associated with thyroid cancers." (PMID 36133306, 2022). "It has been found that BRAF inhibitors (vemurafenib) may lead to JAK2/STAT3 signaling activation in BRAF mutant thyroid cancer cell lines." (PMID 36430869, 2022). "Interestingly, WT1 was also upregulated in thyroid cancer samples with mutant BRAF compared with thyroid cancer samples with wild-type BRAF." (PMID 35123502, 2022). "When a BRAF gene mutation activates the downstream MEK->ERK-MAPK signaling pathway and downstream signaling molecules to enhance the expression of proto-oncogenes, it has a certain effect on the development and metastasis of thyroid cancer." (PMID 35865459, 2022). "Therefore, attenuated responses to BRAF inhibition were seen in thyroid cancers in which YAP is in an active state, in large part through this mechanism." (PMID 36476495, 2022). "Using a computer algorithm to identify major driver mechanisms in our PTC cohort, the results showed that, in addition to BRAF mutations, NF1, PMS2, CDC27 and PPP4R2 gene mutations are also involved in the development of thyroid cancer, and joint mutations often occur." (PMID 35865459, 2022). "However, many thyroid cancers show primary or acquired resistance to all BRAF inhibitors available to date." (PMID 36612117, 2022). "Therefore, the use of molecule-targeted BRAF in BRAF-mutated, advanced or metastatic, radioactive iodine (RAI)-resistant thyroid cancer has become a priority." (PMID 36612117, 2022). "The use of the BRAF inhibitor vemurafenib exhibits drug resistance in the treatment of thyroid cancer (TC), and finding more effective multitarget combination therapies may be an important solution." (PMID 35136031, 2022). "One study showed that (V600E) BRAF inhibition could induce the cytoprotective autophagy via LKB1-AMPK signaling in thyroid cancer cells." (PMID 35912012, 2022). "Our findings show the need to do studies comparing key mutations in thyroid cancer such as BRAF and RET between Filipinos and other Asian subgroups to see if they may explain differences in clinical characteristics of thyroid cancer." (PMID 36743179, 2022). "first reported a link between mutations of the TERT promoter and BRAF (V600E) in PTC, and subsequent studies further demonstrated the coexistence of TERT promoter and BRAF(V600E) mutations in thyroid cancers and their association with the most aggressive PTC clinical factors and worse prognosis." (PMID 36004350, 2022). "Although BRAF mutation is considered to play an important role in the formation and progression of thyroid cancers, the effect of resveratrol on ATC cells with BRAF mutation and MAPK signal transduction mediated by BRAF mutation remains unknown." (PMID 36430869, 2022). "Further experiments are needed to clarify whether there is a connection between BRAF V600E and HT in the occurrence and progression of thyroid cancer." (PMID 35784548, 2022). "However, in 2018, two other inhibitors of this pathway, Dabrafenib (BRAF) and Trametinib (MEK), were approved in the treatment of BRAF-mutated advanced thyroid cancers." (PMID 35053446, 2022). "Hence, primary resistance of BRAF-mutant thyroid cancer cell lines to vemurafenib is overcome by HER kinase inhibitors and further abrogated by YAP inhibition in vitro and in vivo." (PMID 36476495, 2022).
thyroid cancer (continued). "Genetic alterations such as BRAF and TERT mutations can also affect the survival rate of thyroid cancer patients Ferroptosis, a recently discovered type of programmed cell death, appears to play a critical role in carcinogenesis and cancer therapy efficacy, according to mounting data." (PMID 35741758, 2022). "The two most common types of thyroid carcinoma, papillary and follicular carcinoma, harbor four non-overlapping genetic alterations—BRAF and RAS point mutations and RET/PTC and PAX8/PPARγ rearrangements in more than 70% of cases." (PMID 35634500, 2022). "Importantly, further analysis using dataset of Thyroid carcinoma (THCA) from The Cancer Genome Atlas (TCGA) (n = 501) revealed that TBX3 expression was positively correlated with BRAF levels, suggesting that their functional coupling is clinically important." (PMID 35332119, 2022). "Single gene testing, BRAF V600E, proved great accuracy in diagnosing thyroid carcinoma and also, a good decrease of thyroid surgeries due to single-gene positive results meaning that only one gene detection could predict ROM as well as NGS panels." (PMID 35453992, 2022). "In thyroid cancer with BRAFV600E mutations, SMOC2 expression is reduced, which suggests that the use of BRAF inhibitors may promote the expression of SMOC2 and improve the prognosis of patients." (PMID 34923978, 2021). "Based on analyses of FRMD5 expression in human thyroid cancer tissue, it was concluded that the high expression of the FRMD5 gene may be associated with the presence of the BRAF V600E genetic aberration." (PMID 34201607, 2021). "Based on analyses of FRMD5 expression in human thyroid cancer tissue, it was concluded that high expression of the FRMD5 gene may be associated with the presence of the BRAF V600E genetic aberration." (PMID 34201607, 2021). "However, targeting TGFβ/activin-induced pSMAD augmented MAPK inhibitor effects on iodine incorporation into BRAF tumor cells, indicating that these two pathways exert interdependent effects on the differentiation state of thyroid cancer cells." (PMID 33890869, 2021). "With the understanding of BRAF, RAS mutations, and RET/PTC rearrangements in thyroid cancer, researchers still need to identify the existence of unknown genetic or epigenetic alterations within the subpopulation of CSCs." (PMID 33669363, 2021). "Therefore, our results raise the question about the clinical utility of BRAF, KRAS, NRAS, and TERT promoter mutation analysis using ctDNAs of patients with thyroid cancers." (PMID 33915745, 2021). "Our results show, for the first time by the analysis of metabolomic profiles, that the pro-oxidant effect of vitamin C in BRAF mutant thyroid cancer cells induces the inhibition of glycolysis and alteration of TCA cycle via NAD+ depletion, leading to cell death." (PMID 34065197, 2021). "Starting from their primary application in melanoma cancer patients with BRAFV600E mutation, in which high efficiency in tumor growth inhibition had been initially observed, the possibility of exploiting BRAF inhibitors has been extended also to thyroid cancer patients." (PMID 34072194, 2021). "The current molecular markers that have received the most attention in thyroid cancer include BRAF." (PMID 34319022, 2021). "There are few studies investigating BRAF fusion in pediatric thyroid cancer patients." (PMID 34206589, 2021). "Histone modification inhibitors and BRAF inhibitors in thyroid cancer." (PMID 34923978, 2021). "BRAF V600E mutation, which constitutively activates MEK phosphorylation and MAPK/ERK signaling pathway, is the most prevalent genetic alteration in follicular-derived thyroid cancer, particularly in PTC." (PMID 34221969, 2021). "Here, we performed an analysis on the role of FRMD5 in thyroid cancer specimens and cell lines, as we found significant discrepancies in FRMD5 expression between BRAF- and RET-mutated PTCs, as well other types of TCs (TCGA and microarray data analysis of clinical specimens)." (PMID 34201607, 2021).
thyroid cancer (continued). "Moreover, recent evidence suggests that the acquisition of resistance to SRC inhibition in BRAF-mutant thyroid cancer cells increases the expression of pro-inflammatory cytokines and pro-invasive metalloproteases, promoting a more invasive phenotype." (PMID 34771624, 2021). "Since in BRAF wild-type thyroid cancer cells (TPC-1) and control cells (Nthy-ori3-1) exposure to 5 mM vitamin C did not affect ROS perturbations and exhibited low sensitivity to cytotoxic effect, the analysis of metabolic profiles was restricted to B-CPAP and K1 cells." (PMID 34065197, 2021). "Therefore, several genetic tests have been proposed as useful in the diagnosis of thyroid cancer, including tests for BRAF and NRAS mutations, and RET translocation tests; in fact, BRAF mutations have been reported in 30–80% of PTC cases." (PMID 33598460, 2021). "In skin and thyroid cancers, BRAF mutations were common in MB 9 but not in the other classes of MBs." (PMID 34930241, 2021). "This is observed in patients with iodine refractory thyroid cancer, with poorly differentiated, Hürthle cell cancer, PTC with aggressive features (tall cell variant) or with the BRAF V600E mutation and less frequently in patients with well differentiated papillary or follicular carcinoma." (PMID 34638232, 2021). "Different signaling pathways and BRAF inhibitors in thyroid cancer." (PMID 34923978, 2021). "The overall impact of simultaneous BRAF and RAS mutations remains unclear in the setting of thyroid cancer." (PMID 33716974, 2021). "In pilocytic astrocytomas, the KIAA1549 and BRAF genes are frequently found fused as a result of tandem duplication, and in papillary thyroid cancers and thyroid carcinomas, inversion events are most often the cause of RET-CCDC6 and APAK9-BRAF gene fusions, respectively." (PMID 34573358, 2021). "Follicle-like structures were counted in seven fields for each of the six analyzed thyroids for each genotype, confirming that such structures are significantly more represented in thyroid cancers of BRAF FOXE1+/− mice with respect to that of BRAF FOXE1+/+ mice." (PMID 33375029, 2020). "CYP2S1 knockdown selectively inhibited cell proliferation, migration, invasion and tumorigenic potential in nude mice, and promoted cell apoptosis in BRAFV600E mutated thyroid cancer cells, but not in BRAF wild-type ones." (PMID 32913191, 2020). "However, in terms of diagnostic utility, BRAF, NRAS, and TERT promoter mutations have shown greater potential due to the high prevalence and clinical features in thyroid cancer." (PMID 33247684, 2020). "The results showed that CYP2S1 knockdown significantly inhibited cell proliferation in BRAFV600E-mutated thyroid cancer cell lines, but not in BRAF wild-type ones, also supported by colony formation assays." (PMID 32913191, 2020). "We next investigated whether ADAR1 expression is altered during the earliest steps of thyroid tumorigenesis driven by RAS and BRAF, the two main oncogenes in thyroid cancer." (PMID 32157211, 2020). "As expected, CYP2S1 knockdown strongly induced cell apoptosis in BRAFV600E-mutated thyroid cancer cell lines, but not in BRAF wild-type ones." (PMID 32913191, 2020). "Nonetheless, nearly 30% of thyroid cancer patients may face over- or undertreatment in a condition based on BRAF status alone." (PMID 33158279, 2020). "The 2015 American Thyroid Association Management Guidelines for Adult Patients with Thyroid Nodules and Differentiated Thyroid Cancer listed TERT, alone or in combination with BRAF, as potentially helpful to risk stratify patients in conjunction with other clinicopathological risk factors." (PMID 32849278, 2020). "Taken together, the additional molecular testing of BRAF, NRAS, and TERT promoter mutations not only enabled the identification of thyroid malignancies in FNAB cytology but also allowed the prediction of the aggressive characteristics of thyroid cancer." (PMID 33247684, 2020).
thyroid cancer (continued). "All of the relevant studies mainly demonstrate the influence of BRAF V600E on thyroid cancer." (PMID 33520689, 2020). "By contrast, IL6/STAT3 axis mediated resistance to BRAF inhibitors in thyroid carcinoma cells." (PMID 32851683, 2020). "The BRAF status and stimulated thyroglobulin levels at ablation time improve the ATA risk stratification of differentiated thyroid cancer; therefore, even A-hTg could be included in risk classification factors." (PMID 31093278, 2019). "Point mutations in the BRAF or RAS gene or RET/PTC rearrangements, all of which lead to constitutive activation of the mitogen-activated protein kinase (MAPK) signaling pathway, can be found in approximately 70% of thyroid cancer patients." (PMID 31183073, 2019). "Although, huge amount of research work have illustrated that many signaling pathways and genes (such as RAS, MAPK and PI3K/Akt signaling pathways; as well as gene BRAF, RAS, RAF, MEK and ERK, etc.), were associated with the occurrence, development, and metastasis of thyroid cancer." (PMID 31384179, 2019). "Detection of BRAFV600E mutation for diagnosis of thyroid cancer is well documented, however studies not always concord regarding the utility of BRAF detection for prognosis and survival of patient with thyroid cancer." (PMID 31810221, 2019). "It is well-documented that RET/PTC1 is the predominant type of gene rearrangements in the pediatric PTC, and that the frequency of sporadic thyroid cancer cases harboring the RET/PTC rearrangements decreases with age, while those with the BRAF mutation becomes more common." (PMID 31480712, 2019). "Mutations in BRAF and RAS are well characterized in thyroid cancer." (PMID 30885146, 2019). "Moreover, the availability of already approved BRAF inhibitors offers an opportunity to employ this treatment strategy in case of BRAF-positive progressive thyroid cancers." (PMID 31810221, 2019). "In parallel, the various thyroid cancer tissues collected in our study showed loss of IGFBP7 expression regardless of BRAF status." (PMID 31183073, 2019). "Indeed, genetic alteration in BRAF (BRAFT1799A) is the most frequent event that leads to thyroid cancer development, indicating the importance of BRAF protein in thyroid cell oncogenesis." (PMID 30881348, 2019). "Importantly, PLX4720 was able to reduce the migration of thyroid cancer cells, but this effect occurred only in those cells in which PLX4720 also inhibited the secretion of CXCL8 (the BRAF V600E mutated ones)." (PMID 31762942, 2019). "A recent study by our group showed that the BRAF-inhibitor PLX4720 reduced CXCL8 secretion in several BRAFV600E mutated thyroid cancer cell lines (8505C, 8305C, BCPAP), but not in RET/PTC rearranged ones (TPC1)." (PMID 31762942, 2019). "The relevance of BRAF in thyroid cancer has been noted by a large number of authors e.g.39." (PMID 31530827, 2019). "TCGA analysis also indicated a majority of thyroid cancers to be RAS or BRAF mutant." (PMID 31426419, 2019). "Indeed, coexistence of BRAF V600E and TERT promoter mutations was shown to be associated with increased expression of TERT in thyroid cancer." (PMID 31810221, 2019). "It was reported that the genes, coding the MAPK/ERK and PI3K/AKT signaling cascade proteins (e.g., RET, RAS, BRAF, PI3K, PTEN, AKT), were significantly mutated in thyroid cancer, which contributed to aberrant activations of MAPK/ERK and PI3K/AKT signaling pathways of thyroid cancer." (PMID 31384179, 2019). "BRAF and TERT mutations have been extensively related to prognosis in thyroid cancer." (PMID 30884810, 2019). "Unlike patients with wild type BRAF thyroid cancer, a linear association between thyroid cancer mortality and age in patients with BRAF p.V600E mutations has been observed and has been found to be independent to other clinicopathologic risk factors." (PMID 31835496, 2019).